IFNA2 (interferon alpha 2)
Diseases named in the same sentence as IFNA2 in open-access papers (continued):
Sharing a sentence is not in itself a finding about the gene and the disease.
chronic hepatitis C (11 papers, 2009 to 2024). "Interferon alpha-2b (IFN-α2b) is an essential cytokine widely used in the treatment of chronic hepatitis C and hairy cell leukemia, and serum albumin is the most abundant plasma protein with numerous physiological functions." (PMID 38473998, 2024). "Interferon alpha-2b (IFNα-2b) is an important therapeutic product in the treatment of chronic Hepatitis C and hairy cell leukaemia; however, its downstream processing is hindered by the high cost of conventional purification strategies." (PMID 36824351, 2023). "Peg-Intron® (interferon alpha 2B) is a peglated polymer nanoparticle of interferon alpha 2B used in chronic hepatitis C with high anticancer effect." (PMID 29622013, 2018). "The incidence of anti-IFN antibodies appears to be higher in patients with RRMS treated with recombinant IFNβ1 than in patients with chronic hepatitis C treated with either native or pegylated IFNα2." (PMID 27713294, 2010). "We report the case of a 46-year-old Greek man who developed severe aplastic anemia during treatment with pegylated interferon alpha 2a for chronic hepatitis C virus infection." (PMID 20704699, 2010). "In addition, to the best of our knowledge there are no reported cases of patients with chronic hepatitis C virus infection developing aplastic anemia associated with pegylated interferon alpha 2a treatment." (PMID 20704699, 2010). "Pegylated interferon alpha 2a, alpha 2b and ribavirin have been included to the National List of Essential Medicines (NLEM) for treatment of only chronic hepatitis C genotypes 2 and 3 in Thailand." (PMID 27492396, 2016). "There are also case reports of demyelinating neuropathies developing during IFNα2 treatment of patients with chronic hepatitis C without cryoglobulinemia." (PMID 27713294, 2010). "Pegylated interferon alpha 2 (a or b) plus ribavirin is the most effective treatment of chronic hepatitis C but a large proportion of patients do not respond to therapy." (PMID 19493343, 2009).
breast carcinoma (9 papers, 1985 to 2022). "The evaluated PD-L1 level was found to be associated with high IFNα2 and TNFα in breast cancer patients." (PMID 35053979, 2022). "The antagonistic associations on breast cancer ER status could possibly be due to over saturation of the deleterious effects resulting from low vitamin D and high IFNα2 levels." (PMID 24473087, 2014). "Both IFNα2 and TNFα levels were significantly high in breast cancer patients with high PD-L1 levels." (PMID 35053979, 2022). "Effectiveness of recombinant DNA (rDNA) human interferon alpha 2 (IFN alpha 2) in advanced breast cancer was evaluated in 14 patients who had received prior endocrine and/or cytotoxic therapy." (PMID 3917678, 1985). "This study revealed a significant association between serum PD-L1 and IFNα2 and TNFα levels in breast cancer, though not in normal controls." (PMID 35053979, 2022). "Few studies have shown the prognostic value of CBWD1, CWC25, IFNA2, KRT27, or ZDHHC21 in breast cancer, and subsequent studies are expected." (PMID 36077687, 2022). "In this study, we examined the combinational associations of serum levels of 25OHD with plasma levels of three cytokines, IFNα2, TNFα and IL5, as well as ten cytokine ratios, on ER status of breast cancer." (PMID 24473087, 2014).
hairy cell leukemia (9 papers, 2013 to 2025). Hairy cell leukemia (HCL) is a rare type of leukemia in which abnormal B-lymphocytes are present in the bone marrow, spleen and peripheral blood. "The FDA’s approval of interferon-alpha 2 (IFN-α2) for the treatment of hairy cell leukemia in 1986 marked a major transitional point in cancer-directed immunotherapy." (PMID 34572775, 2021). "Interferon-alpha 2 was initially approved for use in hairy cell leukemia (HCL) after studies showed that IFN-a2 demonstrated a high response rate in patients with progressive HCL." (PMID 30333937, 2017).
hepatitis C (9 papers, 2010 to 2024). "A pro-apoptotic effect of Ocoxin on activated HSC could explain some of the beneficial outcomes found in clinical studies carried out with hepatitis C patients, in which treatment with Ocoxin either by itself or combined with interferon alpha-2b and ribavirin caused a reduction of fibrosis." (PMID 35239161, 2023). "In a hepatitis C replication assay, the EC50 values exhibited a narrow range of 2- to 6-fold differences among the IFNs (IFNα7: 36 fM, IFNω: 37 fM, IFNα2(YNS, H57Y, E58N, and Q61S): 20 fM, wild-type IFNα2: 116 fM)." (PMID 39169031, 2024).
HIV-1 infection (8 papers, 2011 to 2022). The type species of lentivirus and the etiologic agent of acquired immunodeficiency syndrome (AIDS). "These cytokines significantly inhibited HIV-1 replication in vitro, but human clinical trials with IFNα2 showed only moderate or no inhibitory effects on HIV-1 infection." (PMID 33064743, 2020).
chronic hepatitis B (7 papers, 2012 to 2024). "However, IFNα2 is still the standard treatment option for chronic hepatitis B patients, but only about 30% of patients respond to the therapy, of which only a few patients show complete viral clearance." (PMID 35126368, 2021). "Pegylated interferon alpha-2a (peg-IFN α-2a) and entecavir (ETV) are both recommended as the first-line antiviral drugs for chronic hepatitis B (CHB) at present." (PMID 35854256, 2022).
multiple sclerosis (6 papers, 2013 to 2026). A progressive autoimmune disorder affecting the central nervous system resulting in demyelination. "In clinical practice, it is interesting to note that the antitumor efficacy of administered IFNα2 is associated with the development of autoimmune manifestations, whereas IFNβ is routinely used for treatment of multiple sclerosis, which is considered to be an inflammatory autoimmune disease." (PMID 23472200, 2013). "We chose to study IFNα2 and β because these two subtypes are routinely used in clinic for pathologies as diverse as chronic viral infection, cancer or multiple sclerosis." (PMID 23472200, 2013). "IFN specialization is also evident in the clinical use of recombinant subtypes, with IFNB1 being the most effective for the treatment of multiple sclerosis, whereas IFNA2 preparations are preferred for the treatment of chronic viral infections and some malignancies." (PMID 35217532, 2022).
hepatocellular carcinoma (5 papers, 2014 to 2025). A malignant tumor that arises from hepatocytes. "Relevant in vitro studies have found that interferon alpha 2a combined with IL‐2 can significantly improve the inhibitory effect on HepG2.2.15 hepatoma cells." (PMID 36381411, 2022).
lymphoma (5 papers, 2013 to 2024). A malignant (clonal) proliferation of B- lymphocytes or T- lymphocytes which involves the lymph nodes, bone marrow and/or extranodal sites. "In this study we extended the reported potential of CD20-targeted attenuated IFNα2 in murine and cancer cell line models, to humanized PDX models as a novel approach to treat lymphoma." (PMID 38831452, 2024).
metastatic melanoma (5 papers, 2007 to 2024). A melanoma that has spread from its primary site to another anatomic site. "Given their immunologic effects, low-dose interleukin-2, granulocyte-monocyte colony stimulating factor and interferon alpha-2b produce durable remissions in patients with metastatic melanoma, and they have been used as postoperative adjuvant therapies." (PMID 17650346, 2007). "In addition, responses have been reported in clinical trials evaluating bevacizumab in combination with interferon alpha 2B, interferon alpha 2A or chemotherapy in patients with metastatic melanoma." (PMID 22719881, 2012). "While some phase II studies have evaluated the use of bevacizumab in concert with interferon alpha 2B, interferon alpha 2A or chemotherapy, to the best of our knowledge this is the first study evaluating bevacizumab monotherapy in metastatic malignant melanoma." (PMID 22719881, 2012).
renal cell carcinoma (5 papers, 1990 to 2025). "Treatment with anti-PD-1, anti-CTLA-4, or interferon alpha-2b was given to patients diagnosed with metastatic or unresectable melanoma, renal cell carcinoma (RCC), non-small cell lung cancer (NSCLC), or neuroendocrine tumors (NET)." (PMID 40406094, 2025). "Cytokine-based immunotherapy, including interleukin 2 (IL-2) and recombinant human interferon-alpha 2a (IFN-α2a), is the first approved immunotherapy for renal cell carcinoma." (PMID 35686121, 2022).
uveitis (5 papers, 2013 to 2024). An inflammatory process affecting a part of or the entire uvea. "Focusing on patients with uveitis, SU showed increased IFNα2 (p = 0.004) and IFNγ (p < 0.002) serum concentrations compared to that in TBU." (PMID 39309852, 2024). "Comparison of patients with uveitis only revealed comparable results with significantly (p < 0.001) higher serum anti-IFNα2 and anti-IFNγ antibody levels in TBU compared to those in SU; these concentrations were again comparable to Indonesian HCs." (PMID 39309852, 2024). "For uveitis cases specifically, IFNα2 was detected in 85 % of sarcoid uveitis (SU) and 33 % of tubercular uveitis (TBU) cases." (PMID 39309852, 2024). "Regarding uveitis, positivity for serum IFNα2 was more frequently observed in SU (11/13 patients: 85 %; p = 0.015; Fisher's exact test) than TBU (4/12 patients: 33 %)." (PMID 39309852, 2024). "A new clinical study suggests that interferon alpha-2a is safe and well-tolerated in the treatment of refractory uveitis and macular edema, and it is an option for patients with persistent refractory UME." (PMID 35280901, 2022). "Other studies have shown that for uveitis patients with refractory CME, systemic treatment with interferon alpha-2b can significantly improve CME and vision." (PMID 35280901, 2022). "We observed that patients with TBU had reduced serum IFNα2 concentrations compared to that in TB cases without uveitis." (PMID 39309852, 2024). "Therefore, we used highly-sensitive immunoassays and bioassays to measure IFNα2, IFNγ, IFN activity, and IFN-autoantibodies in serum from patients with active TB and sarcoidosis, with and without uveitis, and additionally explored potential diagnostic utility." (PMID 39309852, 2024).
bladder cancer (4 papers, 2013 to 2025). "Interferon-alpha-2B has further been studied independently for non-invasive bladder cancer as intravesical administration for patients who failed BCG therapy." (PMID 25515347, 2014). "A large phase II trial has been previously conducted evaluating interferon-alpha 2B with The Bacillus Calmette–Guérin (BCG) vaccine in non-invasive bladder cancer." (PMID 25515347, 2014).
glioma (4 papers, 2022 to 2025). A benign or malignant brain and spinal cord tumor that arises from glial cells (astrocytes, oligodendrocytes, ependymal cells). "To overcome the immunosuppressive tumor microenvironment, we recently explored and demonstrated that multifunctional CAR T cells, additionally transfected with mRNA encoding for the cytokines IL-12 and IFNα2, were able to cure glioma-bearing mice." (PMID 39889712, 2025). "Consequently, we investigated whether also the co-transfection of NK cells and macrophages with CAR-, IL-12-, and IFNα2-encoding mRNAs could similarly improve the survival of glioma-bearing mice." (PMID 39889712, 2025).
Hepatitis (4 papers, 2009 to 2021). Inflammation of the liver. "In our previous study, we reported the high yield production of recombinant IFNα2–Tα1 comprising IFNα2 and Tα1 for use as a substitute of IFNα2 and Tα1, which are used in combination for hepatitis and cancer therapy." (PMID 34203928, 2021). "Studies show that the use of IFNα2 and Tα1 in combination is more effective and less toxic in comparison to when both are used individually for the treatment of cancer and hepatitis." (PMID 34203928, 2021).
prostate carcinoma (4 papers, 2013 to 2023). A carcinoma that arises from epithelial cells of the prostate gland. "However, it was demonstrated that the concentrations of recombinant IFNα2 used (5–10×106 U/m2, three times a week) lead to an intolerable toxicity in patients with advanced prostate carcinoma." (PMID 23913484, 2013). "Moreover, a high concentration of IFNA2 was related to advanced prostate carcinoma." (PMID 36376815, 2022).
Sepsis (4 papers, 2019 to 2025). Sepsis is defined as life-threatening organ dysfunction caused by a dysregulated host response to infection. "We analyzed whether the polymorphism was correlated with the cytokine expression of IL1β, IFNα2, IFNγ, TNF-α, IL-33, IL12p70, MCP-1, IL-6, IL-10, IL-17a, IL-18, or IL-23 to further investigate the effect of the polymorphism in sepsis patients." (PMID 38338680, 2024). "The MS-IFNB1 Z scores were higher than the PBMC-derived Z scores, but IFNW1, IFNA2, and IFNB1 were still highly significant (Z > 3) for all SLE WB, PBMC, and affected tissues, the control dermatomyositis dataset, but not the sepsis dataset." (PMID 31044165, 2019).
autoimmune disease (3 papers, 2021 to 2025). A disorder resulting from loss of function or tissue destruction of an organ or multiple organs, arising from humoral or cellular immune responses of the individual to their own tissue constituents. "A Kruskal–Wallis test with Dunn’s post testing for multiple comparisons revealed significant differences between the SLE patients and pSS and cHCV patients, with a greater presence of low values in patients with autoimmune diseases suggesting a higher proportion of IFNα2 protein." (PMID 33941444, 2021).
chronic granulocytic leukaemia (3 papers, 1990 to 2021). "Thus, IFNα2 has been used to treat chronic hairy cell leukemia chronic myelogenous leukemia, non-Hodgkin’s lymphoma in combination with chemo-therapy, and is used as an adjuvant to surgical restriction for the treatment of malignant melanoma." (PMID 27713294, 2010). "We decided to study the effects of type I interferon α 2 (IFNa2; IFN hereafter) on human HAP1 cells, a chronic myeloid leukaemia (CML)-derived cell line, in the presence or absence of the USP18 gene." (PMID 33214684, 2021).
Cirrhosis (3 papers, 2021 to 2023). A chronic disorder of the liver in which liver tissue becomes scarred and is partially replaced by regenerative nodules and fibrotic tissue resulting in loss of liver function. "Upregulation of type I (Ifn) encoding genes (Ifna2 and Ifnar1), important in first line defense against microbial invasion and loss of immune tolerance were seen in inflammation and cirrhosis stages compared to all other timepoints (all P < 0.01)." (PMID 33858327, 2021). "Using immunohistochemistry, quantitative polymerase chain reaction, and immunofluorescence techniques, we evaluated the therapeutic effect of UC-MSCs pretreated with interferon alpha 2 (IFN-α2) (pre-MSCs) in an animal model of cirrhosis." (PMID 37980535, 2023).
colorectal cancer (3 papers, 1994 to 1996). A primary or metastatic malignant neoplasm that affects the colon or rectum. "The disposition of 5-fluorouracil (FUra) was studied in 19 colorectal cancer patients during treatment with FUra and high-dose leucovorin (LV) with or without interferon alpha 2a (IFN-alpha)." (PMID 7917928, 1994).
conjunctival intraepithelial neoplasia (3 papers, 2021 to 2023). "One of the non-responders ocular MMP was even diagnosed with conjunctival intraepithelial neoplasia during the follow-up period, requiring six applications of interferon-alpha-2b." (PMID 35887866, 2022).
Hypertension (3 papers, 2013 to 2023). The presence of chronic increased pressure in the systemic arterial system. "Hypertension progression was associated with VEGF-A, IL-6, IL-4, and MCP-3, while newly detected hypertension was linked to IL-9, TNFa, IL12(p40), IFNa2, and EGF." (PMID 37629267, 2023).
multiple myeloma (3 papers, 1994 to 2006). "A 71-year-old Chinese male was referred for severe dry eyes who suffered from multiple corneal melting ulcers and underwent a long-term and high-dosage interferon alpha-2b (INFα-2b) treatment for multiple myeloma (MM)." (PMID 23674995, 2006). "In clinical trials with interferon alpha 2b (IFN-alpha 2b) as maintenance therapy for multiple myeloma, the therapeutic benefit is inconclusive." (PMID 8519671, 1995). "In a study of 29 patients who were receiving or had received interferon alpha 2b (IFN-alpha 2b) as maintenance therapy for multiple myeloma, antibodies were detected in 58% (17/29) of patients measured by a solid-phase enzyme-linked immunosorbent assay (ELISA)." (PMID 7917911, 1994).
psoriasis (3 papers, 2010 to 2022). An autoimmune condition characterized by red, well-delineated plaques with silvery scales that are usually on the extensor surfaces and scalp. "Given the increased IFNA2 expression in anti-TNF-induced paradoxical psoriasis, we investigated whether TNF blockade would enhance IFN-α production by pDCs directly." (PMID 29295985, 2018). "In contrast, type I IFNs IFNA2 and IFNB1 expression was greatly increased in paradoxical psoriasis relative to chronic plaque psoriasis." (PMID 29295985, 2018).
schizophrenia (3 papers, 2018 to 2023). A major psychotic disorder characterized by abnormalities in the perception or expression of reality. "In differentiating neurons, the expression of Ifna2 affects their response to inflammatory cytokines, which is consistent with molecular mechanisms involved in schizophrenia and autism spectrum disorder." (PMID 29529077, 2018).
co-infection (2 papers, 2021 to 2022). "The top three markers contributing most to overall network density by AUC in the subgroup of those without HIV-1 co-infection were CXCL10, C-reactive protein, and IFNα2, whereas the top three markers in the subgroup of those with HIV-1 co-infection were IL-17A, IL-1β, and TNFα." (PMID 34386782, 2021).
Hepatic steatosis (2 papers, 2021 to 2024). Steatosis is a term used to denote lipid accumulation within hepatocytes. "Some researchers have suggested that hepatic steatosis induced by 5-FU-containing therapy is reversible, although treatment regimens used in these studies consisted of additional agents such as levamisole and interferon alpha-2a." (PMID 34436031, 2021).
leukaemia (2 papers, 2023 to 2025). "We have used HAP1 cells as a model for CML, as HAP1 cells are derived from CML patient cells and have the BCR-ABL gene, which is common in leukaemia’s, turning the myeloid cell into a chronic myeloid cell, and IFN-I (IFNα2) as a treatment." (PMID 37958498, 2023).
lupus erythematosus (2 papers, 2019 to 2024). An autoimmune, connective tissue chronic inflammatory disorder affecting the skin, joints, kidneys, lungs, heart, and the peripheral blood cells. "Discoid lupus erythematosus (DLE) was significantly separated from control skin by all of the signatures (p < .05); IFNB1 had the greatest size (Hedge’s g = 12.4) followed by IFNW1 (g = 9.7), IFNG (g = 8.7), IFNA2 (g = 7.9), IL12 (g = 5.2), and TNF (g = 2.8)." (PMID 31044165, 2019).
lymphopenia (2 papers, 2015 to 2024). Reduction in the number of lymphocytes. "IFNα2 therapy was long known to have undesirable clinical side-effects including fever, fatigue and lymphopenia." (PMID 26529416, 2015).
mesothelioma (2 papers, 2019 to 2021). A usually malignant and aggressive neoplasm of the mesothelium which is often associated with exposure to asbestos. "Historically, administration of IFNA2 to patients with mesothelioma has occasionally induced complete regression." (PMID 34580349, 2021). "A dampened effector response (IFNα2, IFNγ, MIP1α, TNFα and TNFβ) was detected in NSCLC PE, but not mesothelioma or benign PE." (PMID 31741710, 2019).